ANXA2 (annexin A2)
Diseases named in the same sentence as ANXA2 in open-access papers (continued):
Sharing a sentence is not in itself a finding about the gene and the disease.
tumor (359 papers, 2009 to 2026). "Its specific recognition target is the Ca2+-dependent membrane-binding protein Annexin A2, whose expression is closely associated with tumor stemness, leading to metastasis and poor clinical prognosis." (PMID 40948789, 2025). "In the SP2/0 myeloma mice model infected with T. spiralis, genes encoding RpL41, NKTR, Rbbp4, and ANXA2 were enriched in tumor cells, suggesting a potential role in tumor growth inhibition." (PMID 40402283, 2025). "Parallel observations in the circRNA combination cohort revealed sustained downregulation of key classical oncogenes (PIK3CA) and novel tumor-associated genes (ANXA2, KIF2A, NCAPG2, PAIP1)." (PMID 40426998, 2025). "High ANXA2 expression is associated with poor prognosis in several cancers, underscoring its role in tumor escape mechanisms." (PMID 40018411, 2025). "ANXA2 is an emerging tumor biomarker that promotes cancer progression and is linked to poor prognosis." (PMID 40069750, 2025). "In other cases, Vδ1+ T cells interact with protein stress ligands such as non-classical MHC class I proteins, MICA/B and ULBPs, via Vδ1+ T cell surface NKG2D receptor, and annexin A2, a molecule linked to tumor cell stress and apoptosis." (PMID 40746558, 2025). "AnxA2 has been implicated in tumor invasion and metastasis in several cancers, so chronic or systemic activation of AnxA2 pathways requires caution in populations at risk for malignancy." (PMID 41550928, 2025). "In RCC, Annexin A2 was reported to be associated with higher tumor grade, metastatic potential and poor prognosis." (PMID 38519766, 2024). "Abnormal ubiquitination of ANXA2 has been implicated in promoting metastasis of certain tumor types." (PMID 39594718, 2024). "We analyzed the differential expression of Annexin A2 in different tumors and its relationship with cancer prognosis, immune cell infiltration, DNA methylation, tumor mutation burden (TMB), microsatellite instability (MSI) and mismatch repair (MMR)." (PMID 36713082, 2023). "Previous studies in FBC have shown that increased ANXA2 gene expression is associated with drug resistance and tumor recurrence." (PMID 37685859, 2023). "The angiogenic function of Tppp3+ monocyte is mainly supported by high expression of Anxa1 and Anxa2, encoding proteins involved in tumor angiogenesis and metastasis." (PMID 37483625, 2023). "The Annexin A2 expression was variably associated with infiltration of 24 types of immune cells in 32 tumor microenvironments." (PMID 36713082, 2023). "A recent experiment explored the effect of OC cell-derived exosomal ANXA2 on peritoneal implantation and tumor metastasis and its underlying mechanism." (PMID 36425071, 2022). "Oncogenic roles of transgelin-2 in HCC have been demonstrated, and its high expression is associated with ANXA2, which, in turn, promotes tumor metastasis through the NFκB pathway." (PMID 34575275, 2021). "It turns out that the plant lectin can inhibit tumor cell proliferation, migration and promote apoptosis by block the binding of ANXA2 and galectin-3, causing suppression of EGFR-mediated signaling." (PMID 33995636, 2021). "Together, these results suggest that high expression of AnxA2 found in serum samples of TNBC patients is associated with the high expression and phosphorylation of AnxA2 at Tyr23 in tumor tissues of TNBC patients." (PMID 33374917, 2020). "Subsequently, we established that the high expression of AnxA2 seen in sera of TNBC patients is associated with the phosphorylation status of AnxA2 at Tyr23 in tumor cells." (PMID 33374917, 2020). "To improve the therapeutic efficacy, we focused on a tumor-associated protein called Annexin A2 (ANXA2)." (PMID 29598816, 2018). "Additional examples of RBPs with known oncogenic or tumor suppressive functions that have been linked to EV miRNA sorting include Annexin A2 (ANXA2), Kirsten rat sarcoma (KRAS), Y-box binding protein 1 (YB-1), MEX3C, and Argonaute 2 (AGO2)." (PMID 30071693, 2018).
tumor (continued). "Being critical to tumour invasion pathways, ANXA2 association with distinct CRC subtypes places it as an important player in CRC progression, a useful tool for screening patients with CRC and a possible target for new drugs aimed to interfere with the EMT." (PMID 30050103, 2018). "ANXA2 gene encodes a calcium-dependent phospholipid-binding protein, which involves in processes of pathology and physiology of many neoplasms." (PMID 29291003, 2017). "Together, our results provide mechanistic insights into the association of intracellular annexin A2 with the cytoskeletal machinery in tumor cells, and exploit its role as an intracellular target in cancer progression." (PMID 28652618, 2017). "The results were different from previous findings that upon loss of Annexin A2 tumor cells undergo apoptosis through activation of both JNK and p38MAPK signaling under hydrogen peroxide stimulation." (PMID 28886730, 2017). "Then, using a tissue chip containing 42 clinical NB samples, we found that strong expression of ANXA2 was closely associated with advanced stage, greater number of chemotherapy cycles, tumor metastasis and poor prognosis." (PMID 28814318, 2017). "Upon loss of ANXA2, tumor cells undergo apoptosis through proapoptotic p38MAPK (mitogen-activated protein kinase)/c-Jun N-terminal kinase (JNK)/Akt signaling under hydrogen peroxide stimulation." (PMID 24591759, 2014). "As GBM1 is known to have recurrent tumors at locations distant from the initial lesion, we found that Annexin A2, a tumor-associated protease which plays a critical role in tumor invasion, is abundant in GBM1." (PMID 23875172, 2013). "Although published data support a crucial role for ANXA2 in tumor progression, the detailed mechanisms underlying this role have yet to be fully elucidated." (PMID 23950866, 2013). "In fact, annexin A2 is proposed as a potential diagnostic/prognostic marker for prediction of tumor malignancy, metastatic recurrence and patient survival." (PMID 23519104, 2013). "There was no statistical association between the positive expression of tissue ANXA2 and age, gender, tumor differentiation, tumor size or HCC recurrence." (PMID 23946789, 2013). "Ex-vivo human cancer studies showed that up-regulation of the reduced form of ANXA2 is associated with protection of the tumor proteins from oxidation." (PMID 22185818, 2011). "The loss of ANXA2-dependent redox regulation during tumor growth was restored by the antioxidant activity of NAC." (PMID 22185818, 2011). "Annexin A2 is closely associated with cell division regulation and tumor growth, and is deregulated in many tumors." (PMID 19638242, 2009). "Immune correlation analyses reveal ANXA2 positively associates with tumour-associated macrophages (TAMs), regulatory T-cells (Tregs), and myeloid-derived suppressor cells (MDSCs) infiltration, while inversely correlating with activated natural killer (NK) cells and dendritic cells (DCs)." (PMID 40234383, 2025). "Interestingly, higher ANXA2 levels are associated with increased survival of patients with PCa suggesting that treatment with SAL has tumor suppressive activity." (PMID 39562436, 2025). "Recently, ANXA2 was shown to play an important role in regulating the expression of tumor-associated fibroblasts (CAFs) and infiltrating immune-related cells, as well as in the synergy between endothelial cells and the tumor microenvironment (TME)." (PMID 41185558, 2025). "Correlation between ANXA2 and tumor-driving mutations was assessed in the Javelin-101 cohort." (PMID 38519766, 2024). "Importantly, they observed that the degree of ANXA2 downregulation correlated with increased tumor invasiveness and loss of differentiation." (PMID 39594718, 2024). "HAR1A deficiency, in turn, stimulated tumor growth and metastasis by activating the ANXA2/p65 axis." (PMID 38688909, 2024).
tumor (continued). "In addition, Annexin A2 expression was differently associated with 47 immune checkpoints, immunoregulators, DNA methylation, tumor mutation burden, microsatellite instability and mismatch repair in pan-cancer." (PMID 36713082, 2023). "ANXA2 has been implicated in cell cycle regulation and regulates tumor cell growth and survival." (PMID 36120574, 2022). "Besides, elevated exo-AnxA2 expression in BC was closely associated with tumor grade, poor overall survival, and poor disease-free survival." (PMID 36499561, 2022). "High expression of exo-AnxA2 levels in BC patients was significantly associated with tumour grade (p < 0.0001), poor overall survival (hazard ratio (HR) 2.802; 95% confidence intervals (CI) = 1.030–7.620; p = 0.0353) and poor disease-free survival (HR 7.934; 95% CI = 1.778–35.398; p = 0.0301)." (PMID 35053279, 2022). "Notably, ANXA2 participates in facilitating host cell infection by HPV16 resulting in a high risk of tumor progression." (PMID 36247003, 2022). "Besides, high expression of exo-AnxA2 levels in BC was significantly associated with tumor grade, poor overall survival and poor disease-free survival." (PMID 33803776, 2021). "Moreover, we further validated the ExoGAG clinical performance in plasma samples from EC patients by analyzing L1CAM and ANXA2, known biomarkers for this tumor, in the isolated EVs, resulting in an improved diagnostic and prognostic value." (PMID 31842290, 2019). "Moreover, our results also demonstrate that the levels of ANXA2 in purified EVs from the plasma of EC patients correlate with the tumor histology, grade, stage, and risk of recurrence, reinforcing their interest as a marker linked to more aggressive tumors." (PMID 31842290, 2019). "Moreover, the 15q22 region, locus of the ANXA2 gene, has been previously shown to be associated with poorly differentiated tumours in advanced cases." (PMID 29377909, 2018). "In conclusion, this pilot proteomics study suggests that tumor expression of ANXA2 in diagnostic samples of a PCa may be predictive for the metastatic potential of that cancer." (PMID 26388710, 2015). "Subsequent studies have implicated ANXA2 in several biological functions including mitogenic signal transduction, fibrinolysis, immune response, proliferation, carcinogenesis and tumor progression." (PMID 23950866, 2013). "Taken together, these results indicate that annexin A2 depletion resulted in a loss of cellular redox regulatory capability, which became critical as these cancer cells were subjected to enhanced oxidative stress in the tumour site in vivo." (PMID 23434659, 2013). "It is then reasonable to propose that ANXA2 depletion from the cancer cells resulted in a loss of cellular redox regulatory capability which became critical as these cancer cells grew into tumors and were subjected to oxidative stress in the tumor site." (PMID 22185818, 2011). "So, here we introduce AnxA2, as a Ca2+-dependent phospholipid-binding protein, and an AnxA2 mRNA-binding protein which has been implicated in many cancers like breast, prostate, ovarian, etc., as it helps cancer cells to migrate, invade, and proliferate in the tumor microenvironment." (PMID 36612209, 2022). "Changes in the expression and spatial distribution of ANXA2 are closely associated with the invasion and metastasis of multiple tumors, and the interaction between ANXA2 and molecules involved in tumor invasion and metastasis may promote these malignant behaviors." (PMID 25362534, 2014). "Proteomic profiling of MSC-exosomes identified key proteins, including ANXA1, ANXA2, EEF2, LGALS1, and PKM2, associated with tumor regeneration and chemotherapy response." (PMID 41683993, 2026). "The anti-ANXA2 monoclonal antibody mAb150 reactivates cancer stem cell cycling by recognizing the N-terminal epitope, disrupting tumour dormancy." (PMID 40234383, 2025).
tumor (continued). "Mechanistically, LINC01614 is packaged into CAF exosomes and transferred to tumor cells, where it binds annexin A2 (ANXA2) and p65 to activate NF-κB signaling." (PMID 41409273, 2025). "We investigated how ANXA2 functions to suppress apoptosis in tumour cells and subsequently promotes tumour cell growth and treatment resistance by counteracting the apoptosis induced by radiation and chemotherapy." (PMID 40234383, 2025). "Knockdown of ANXA2 reduces SAL-induced cellular senescence suggesting that ANXA2 is part of the tumor suppressive program of SAL." (PMID 41264145, 2025). "This demonstrates ANXA2’s role in spatially organizing ICAM-1 distribution to control neutrophil recruitment during immunosuppressive tumour microenvironment remodeling." (PMID 40234383, 2025). "Annexin A2 (Anxa2), which serves as a calcium‐dependent protein, played multiple functions in tumor angiogenesis, cell proliferation, and apoptosis." (PMID 39912333, 2025). "2448-28z CAR bearing the single chain variable fragment (scFv) of an antibody (Ab) discovered by our lab targets the Annexin A2 antigen on tumor cells." (PMID 40248694, 2025). "While ANXA1 was enriched in MVP, pseudopalisading regions, and more diffusely infiltrative GBM peripheries, ANXA2 was elevated in TCs and ECs in comparison to lower-grade tumor samples." (PMID 41366031, 2025). "Tumour cells compensate by overexpressing annexins, including ANXA2, and members of the annexin family promote membrane fusion events and wound healing by binding to negatively charged phospholipids in the plasma membrane." (PMID 40234383, 2025). "Differently, a Vδ3+ T cell clone has shown ability to sense cell stress factors and recognize annexin A2 that binds to cell surface lipids on tumor cells responding to stress and depending on the induction of reactive oxygen species." (PMID 40746558, 2025). "On the basis of these insights, an engineered EV (iEV-150) that displays the tumor-homing peptide iRGD on its surface was developed and loaded with miR-150-3p, utilizing annexin A2 (ANXA2) to enhance selective RNA incorporation." (PMID 40860143, 2025). "Conclusions: iEV-150 integrates ANXA2-mediated miRNA loading, tumor-specific targeting, ferroptosis induction, and immune microenvironment reprogramming." (PMID 40860143, 2025). "Ginsenosides Rg5 and Rk1 block ANXA2-NF-κB p50 interaction, inhibiting NF-κB pathway activation and tumour cell proliferation." (PMID 40234383, 2025). "The ECM-affiliated genes ANXA1 and ANXA2 showed robust spatial enrichment in GBM compared to the grade III tumor." (PMID 41366031, 2025). "Among them, membrane repair and the antioxidant response involve adaptive regulation of ANXA2 in response to mechanical and oxidative stress, and this regulatory mechanism helps tumour cells resist apoptosis induced by stress signals." (PMID 40234383, 2025). "Under starvation induction, ANXA2 mediates the transcriptional activation of Atg7 and enhances autophagic flow, promoting drug resistance in tumour cells." (PMID 40234383, 2025). "AnxA2 is produced by endothelial, trophoblast, epithelial, and tumor cells, macrophages, monocytes, and dendritic cells." (PMID 41550928, 2025). "Once established in the brain, tumor cells release exosomes enriched in miR-105, miR-181c and Annexin A2 that reprogramme astrocytes." (PMID 41562063, 2025). "Despite compelling preclinical evidence of the therapeutic potential of ANXA2-targeting strategies in inhibiting tumour growth, overcoming drug resistance, and improving efficacy, these approaches are still largely in the experimental research phase." (PMID 40234383, 2025).
tumor (continued). "Despite the many mysteries surrounding the role of ANXA2 in regulating tumour cell apoptosis and immune mechanisms, we hope to provide new perspectives for understanding the complex functions of ANXA2 in tumours from the perspective of apoptosis." (PMID 40234383, 2025). "In the review, we describe how ANXA2 regulates apoptosis in tumour cells through its effects on ROS, autophagy, DNA damage response, and glycolysis." (PMID 40234383, 2025). "ANXA2 is expressed in multiple tissues and cell types, including epithelial and endothelium, macrophages, monocytes, trophoblasts, and dendritic and tumor cells." (PMID 40244610, 2025). "In this review, we clarify ANXA2 as a regulator of apoptosis, highlighting one mechanism by which ANXA2 promotes autophagy in tumour cells to inhibit apoptosis." (PMID 40234383, 2025). "The expression of SPOCK1 was significantly positively correlated with ANXA2, implying a potential synergistic role in promoting tumor metastasis." (PMID 40837013, 2025). "Regarding pyroptosis, ANXA2 modulates the tumor microenvironment through the β-catenin signaling pathway, linked to pro-inflammatory factors." (PMID 40018411, 2025). "Recently, there has been increasing recognition of the significant role of ANXA2 in inhibiting apoptosis and promoting immune evasion in tumour cells." (PMID 40234383, 2025). "This review provides a detailed elucidation of the mechanisms by which ANXA2 inhibits tumour cell apoptosis." (PMID 40234383, 2025). "Targeting ANXA2 in cancer therapy not only inhibits tumour cell growth but also enhances the effects of chemotherapy and immunotherapy, presenting a broad application potential." (PMID 40234383, 2025). "We aim for these findings to offer new insights into targeted cancer therapy strategies and inspire more in-depth research on ANXA2 in tumour biology." (PMID 40234383, 2025). "ANXA2 has emerged as a promising prognostic biomarker and modulator of tumor immune microenvironment in various malignancies, including HCC." (PMID 40717977, 2025). "This review summarizes the role and mechanisms of ANXA2 in regulating apoptosis in tumour cells, the connection between apoptosis regulation and tumour immunity, and the potential role of ANXA2 in therapy resistance." (PMID 40234383, 2025). "Higher ANXA2 expression is associated with better survival of PCa patients and suggests that ANXA2 is part of SAL-mediated tumor suppressive activity." (PMID 39562436, 2025). "Studies reveal that suppressing ANXA2 expression or its mRNA significantly inhibits tumour cell growth and metastasis." (PMID 40234383, 2025). "ANXA2 supports angiogenesis in specific tumor-related settings, and its expression level was positively correlated with that of Cpt1a in S100a4+ alv-macro." (PMID 40658605, 2025). "Bioluminescence images showed that the tumor size in the ANXA2 knockdown group was smaller than that in the control group." (PMID 38658569, 2024). "The results of tumor volume and weight analysis showed that the tumor in the ANXA2 knockdown group was smaller than the control group." (PMID 38658569, 2024). "In summary, our data demonstrate that hsa_circ_0013561 promotes EMT and tumor progression via the miR-23b-3p/ANXA2 axis." (PMID 38102461, 2024). "ANXA2 is mainly expressed in endothelial cells, monocytes, macrophages, bone marrow cells, and various tumor cells, and participates in many vital activities such as trans-membrane transport, inflammatory reactions, and muscle cell membrane repair." (PMID 38658569, 2024). "KYSE30 cells with stable ANXA2 knockdown were injected into the subcutaneous area of the armpits of nude mice, tumor sizes were observed using the IVIS Lumina III imaging system." (PMID 38658569, 2024). "LINC00659, originating from CAFs, is delivered to tumor cells and functions as a miR-342-3p sponge, thereby escalating annexin A2 (ANXA2) expression in CRC cells." (PMID 38741166, 2024).